MTARC1 (mitochondrial amidoxime reducing component 1)
Description:
Catalyzes the reduction of N-oxygenated molecules, acting as a counterpart of cytochrome P450 and flavin-containing monooxygenases in metabolic cycles. As a component of prodrug-converting system, reduces a multitude of N-hydroxylated prodrugs particularly amidoximes, leading to increased drug bioavailability. May be involved in mitochondrial N(omega)-hydroxy-L-arginine (NOHA) reduction, regulating endogenous nitric oxide levels and biosynthesis. Postulated to cleave the N-OH bond of N-hydroxylated substrates in concert with electron transfer from NADH to cytochrome b5 reductase then to cytochrome b5, the ultimate electron donor that primes the active site for substrate reduction.
Synonyms: mARC1; MOSC1; FLJ22390
Tractability: Small molecule: a structure with a bound ligand is known. Antibody: UniProt predicts a signal peptide or a membrane-spanning region. PROTAC: ubiquitination databases record sites on it.
Target class: Enzyme; Oxidoreductase
Gene: Protein-coding gene on chromosome 1 (220,786,352 to 220,819,659, forward strand). Ensembl gene ENSG00000186205.
Subcellular location: Mitochondrion outer membrane; Membrane
Subcellular location (Human Protein Atlas): Mitochondria
Pathways (Reactome):
Metabolism: Phase I - Functionalization of compounds
Gene Ontology:
Molecular function: molybdenum ion binding; molybdopterin cofactor binding; nitrate reductase activity; nitrite reductase (NO-forming) activity; nitrite reductase activity; oxidoreductase activity, acting on other nitrogenous compounds as donors; protein binding; catalytic activity; pyridoxal phosphate binding
Biological process: cellular detoxification of nitrogen compound; nitrate metabolic process; nitric oxide biosynthetic process; detoxification of nitrogen compound
Cellular component: mitochondrion; nitric-oxide synthase complex; mitochondrial outer membrane; membrane
Genetic constraint (gnomAD): Loss-of-function variants: 26 observed, 29.32 expected, observed/expected ratio (o/e) 0.89, 90% interval 0.65 to 1.23. The upper end of that interval is the gene's LOEUF score, 1.23, which puts it in group 5 of 6, group 1 being the genes least tolerant of losing a copy. Missense variants: 402 observed, 379.82 expected, observed/expected ratio (o/e) 1.06, 90% interval 0.98 to 1.15. Synonymous variants: 177 observed, 158.33 expected, observed/expected ratio (o/e) 1.12, 90% interval 0.99 to 1.27.
Homologues: Orthologues: chimpanzee MTARC1 (99% identical), pig MTARC1 (85% identical), dog MTARC1 (84% identical), mouse Mtarc1 (80% identical), rabbit MTARC1 (77% identical), guinea pig MTARC1 (77% identical), rat Mtarc1 (74% identical), tropical clawed frog mtarc1 (53% identical), tropical clawed frog mtarc1l (46% identical), zebrafish marc1 (43% identical), Caenorhabditis elegans F56A11.5 (33% identical), Caenorhabditis elegans F53E10.1 (31% identical), and 2 more. Paralogues in human: MTARC2 (65% identical), MOCOS (26% identical).
Diseases named in the same sentence as MTARC1 in open-access papers:
MTARC1 is named in the same sentence as 28 diseases in open-access papers, as found by Europe PMC text mining. Sharing a sentence is not in itself a finding about the gene and the disease. The quoted sentences say what the papers report.
Cirrhosis (24 papers, 2020 to 2026). A chronic disorder of the liver in which liver tissue becomes scarred and is partially replaced by regenerative nodules and fibrotic tissue resulting in loss of liver function. "The second protective variant, MTARC1, was shown to have beneficial effects on hepatic steatosis and cirrhosis and to correlate with improved plasma liver tests and lipoprotein profile." (PMID 36555467, 2022). "We identified 18 sequence variants associated with NAFL and 4 with cirrhosis, and found rare, protective, predicted loss-of-function variants in MTARC1 and GPAM, underscoring them as potential drug targets." (PMID 36280732, 2022). "The MTARC1 lead variant was discovered in a GWAS of cirrhosis, and then found to associate with lower ALT and AST39." (PMID 34315874, 2021). "Recent genome-wide association studies have identified a missense variant p.A165T in mitochondrial amidoxime-reducing component 1 (mARC1) that is strongly associated with protection from all-cause cirrhosis and improved prognosis in nonalcoholic steatohepatitis." (PMID 38723751, 2024). "Analyzing 12,361 all-cause cirrhosis cases and 790,095 controls from eight cohorts, we identify a common missense variant in the Mitochondrial Amidoxime Reducing Component 1 gene (MARC1 p.A165T) that associates with protection from all-cause cirrhosis (OR 0.91, p = 2.3*10−11)." (PMID 32282858, 2020). "A common missense variant within the MTARC1 gene p.A165T, is associated with decreased liver fat, lower ALT, lower total cholesterol, protection from all-cause cirrhosis, and reduction in liver-related mortality." (PMID 39927988, 2025). "Variation at APOE, MTARC1, and MBOAT7 has been found to confer risk of hepatic steatosis and cirrhosis." (PMID 40823170, 2025). "The previously reported NAFLD variants p.Thr165Ala in MTARC1 and p.Ile148Met in PNPLA3 had proportional effects on cirrhosis." (PMID 38632349, 2024). "rs2642438 A>G in MTARC1 (p.Thr165Ala) has very recently been identified as a risk variant in NAFLD and all-cause cirrhosis." (PMID 32720691, 2020). "In our cohort, the protective effect of MTARC1 p.A165T minor allele on liver fibrosis was documented despite the absence of patients with cirrhosis, which could further increase the significance of the effect." (PMID 36555467, 2022). "Despite the lack of difference in recombinant enzyme turnover, GWAS of MTARC1 p.A165T shows remarkably broad protection from liver fibrosis, steatosis, and cirrhosis and a benefit in NASH." (PMID 38723751, 2024).
liver disease (15 papers, 2020 to 2026). "Some variants located in HSD17B13 and MTARC1 offer protective effects, reducing the risk of severe liver disease despite comorbidities such as obesity, and can mitigate the harmful effects of these risk alleles." (PMID 41772607, 2026). "Both rs72613567T>TA in HSD17B13 and rs2642438G>A in MTARC1 were originally identified as GWAS‐significant risk‐reducing loci for liver disease in adults." (PMID 35411667, 2022). "The data from these biochemical and functional assays suggest a mechanism by which the MTARC1 p.A165T variant abrogates enzyme function which may contribute to its protective effect in liver disease." (PMID 38723751, 2024). "However, there are no reports of human genetic associations between variants in the MTARC2 gene and liver disease suggesting that MTARC1 may be the critical mARC enzyme involved in liver pathophysiology." (PMID 39927988, 2025). "siRNA-mediated knockdownof MTARC1 expressionin hepatocytes has been proposed as a strategy for prevention or treatmentof liver diseases like MASH." (PMID 39397364, 2024). "Recently, mitochondrial amidoxime reducing component 1 (MTARC1) rs2642438 and hydroxysteroid 17-beta dehydrogenase 13 (HSD17B13) rs72613567 polymorphisms were shown to have protective effects on liver diseases." (PMID 36555467, 2022).
fatty liver (9 papers, 2020 to 2025). "The decreased risk of developing NAFLD due to the MTARC1 variant was also confirmed in a recent analysis of 9491 cases with fatty liver." (PMID 36555467, 2022). "In conclusion, hepatic steatosis is common among patients scheduled for bariatric surgery, but the MTARC1 and HSD17B13 polymorphisms lower liver injury in these individuals." (PMID 36555467, 2022). "For instance, five variants in or near TM6SF2, PNPLA3, HFE, APOE, and MTARC1 had comparably larger effects on HCC than on hepatic steatosis (p <0.05 by Cochran’s Q test), while HCC-associated variants in HSD17B13, KLF15, and TERT did not significantly associate with steatosis." (PMID 40823170, 2025). "rs2642438G>A in MTARC1 was associated with a lower grade of hepatic steatosis (p = 0.02)." (PMID 35411667, 2022).
non-alcoholic fatty liver disease (7 papers, 2020 to 2023). "The apparent involvement of mARC enzymes in lipid metabolism has received very much attention after a GWAS reported a common polymorphism of the MTARC1 gene, specifically, the mARC1 p.A165T variant, to be correlated with non-alcoholic fatty liver disease (NAFLD) and liver cirrhosis." (PMID 37778733, 2023).
liver fibrosis (6 papers, 2021 to 2026). "The missense variant of the Mitochondrial Amidoxime Reducing Component 1 (MTARC1 p.A165T) has been shown to be protective against hepatic fibrosis in obese individuals and buffers the effects of the PNPLA3 p.I148M allele." (PMID 40833357, 2026). "On the other hand, the rs2642438 polymorphism in the MTARC1 gene showed a significant protective effect against liver fibrosis." (PMID 40650184, 2025). "We also demonstrate that the common missense variant of MTARC1 p.A165T is protective against hepatic fibrosis in obese individuals and ameliorates the harmful effects of the PNPLA3 p.I148M minor allele." (PMID 36555467, 2022). "In the multivariate model, variant MTARC1 was an independent protective factor against liver fibrosis ≥ 1b (OR = 0.52, 95% CI 0.29–0.92; p = 0.03) and ≥1c (OR = 0.51, 95% CI 0.28–0.92; p = 0.04)." (PMID 36555467, 2022). "The increment of liver fibrosis was associated with decreasing frequency of the MTARC1 minor allele (p = 0.03)." (PMID 36555467, 2022). "The increment of liver fibrosis stage was associated with decreasing frequency of the MTARC1 minor allele (p = 0.03)." (PMID 36555467, 2022). "The work contributes significantly to understanding the role of genetic polymorphisms in liver fibrosis associated with MASLD, highlighting the relevance of the MTARC1 gene as a protective factor." (PMID 40650184, 2025). "This is the first study to investigate the relationship between the PNPLA3 rs738409, TM6SF2 rs58542926, GCKR rs1260326 and rs780094, MBOAT7 rs641738, HSD17B13 rs72613567, and MTARC1 rs2642438 polymorphisms in the Brazilian population with MASLD and liver fibrosis." (PMID 40650184, 2025). "In addition, this is the first study to investigates the relationship between the rs738409 (PNPLA3), rs58542926 (TM6SF2), rs1260326 and rs780094 (GCKR), rs641738 (MBOAT7), rs72613567 (HSD17B13), and rs2642438 (MTARC1) polymorphisms in the Brazilian population with MASLD and hepatic fibrosis." (PMID 40650184, 2025). "To understand whether liver-specific loss of mARC1 can also confer protection from the development of MASH and liver fibrosis, we used a GalNAc-conjugated hepatocyte-targeting siRNA to knockdown Mtarc1 specifically in hepatocytes in a therapeutic paradigm in mice fed a GAN diet for 16 weeks." (PMID 39927988, 2025).
steatosis (6 papers, 2020 to 2025). Increased lipid within the cytoplasm of cells. "Another common variant, in MTARC1, reduces the severity of steatosis on biopsy." (PMID 35411667, 2022). "rs2642438G>A in MTARC1 was associated with a lower grade of steatosis (p = 0.016)." (PMID 35411667, 2022). "We observed that Mtarc1 knockdown resulted in reduced steatosis in all 3 zones of the liver lobule and a decrease in both macrosteatosis and microsteatosis." (PMID 39927988, 2025). "In addition, in this HFDHFr model of MASH and fibrosis, fibrosis was predominant in zone 2 (perisinusoidal region) of the liver lobule, and Mtarc1 knockdown resulted in significantly lower zone 2 fibrosis and decreased fibrosis-steatosis co-localization for." (PMID 39927988, 2025). "Similar to our findings, the MTARC1 genotype did not correlate with steatosis in that study." (PMID 36555467, 2022).
hepatocellular carcinoma (4 papers, 2020 to 2024). A malignant tumor that arises from hepatocytes. "MTARC2, which shares a high degree of sequence similarity with MTARC1, was downregulated in human hepatocellular cancer tissues and cells." (PMID 36106120, 2022).
Obesity (4 papers, 2022 to 2026). Accumulation of substantial excess body fat. "In conclusion, we demonstrate that MTARC1 p.A165T, and to a lesser extent, HSD17B13 rs72613567 polymorphism can be protective against NAFLD-related liver injury in patients with obesity scheduled for bariatric surgery." (PMID 36555467, 2022). "Other studies have shown decreases in both hepatic MTARC1 and MTARC2 mRNA concentrations in mice after 24 weeks on a TD190883 (obesity model) diet." (PMID 37778733, 2023).
fibrosis (3 papers, 2020 to 2025). the formation of excess fibrous connective tissue in an organ or tissue in a reparative or reactive process. "Our results suggest a link between the NASH-protective variant in MTARC1 to the metabolism of sphingomyelins and identify distinct molecular patterns associated with each of the NASH-fibrosis variants under investigation." (PMID 32720691, 2020).
atherosclerosis (2 papers, 2020). A disease characterized by the build-up of fatty material and calcium deposition in the arterial wall resulting in partial or complete occlusion of the arterial lumen. "Two variants did, however, associate with differences in lipoproteins that would classically be associated with a lower risk of atherosclerosis: lower LDL-cholesterol and total TG with rs58542926 C>T near TM6SF2, and higher HDL-cholesterol with rs2642438 A>G in MTARC1." (PMID 32720691, 2020).
autoimmune hepatitis (2 papers, 2021 to 2022). Hepatitis caused by autoantibodies. "Our candidate gene study demonstrated the protective effects of MTARC1 p.A165T polymorphism on liver injury in patients with autoimmune hepatitis (AIH)." (PMID 36555467, 2022).
diabetes (1 paper, 2022). "In the univariate model, we detected a trend for protection against NASH conferred by the MTARC1 polymorphism (p = 0.08), whereas the PNPLA3 variant, hyperlipidemia, and diabetes were all associated with a significantly increased risk of NASH." (PMID 36555467, 2022).
thyroid tumorous (1 paper, 2022). "SLC25A15, DIRAS2, PLA2R1, and MTARC1 expression was downregulated in thyroid tumorous tissues with LNM compared thyroid tumorous tissues with NLNM, which was validated using the TCGA dataset." (PMID 36106120, 2022).
tumor (2 papers, 2022 to 2025). "HSD17B13, TM6SF2, PNPLA3, MTARC1, and HLA-DP1 exhibited lower expression in HCC compared with non-tumor liver tissues." (PMID 40823170, 2025). "Comparative analyses of these DEPs revealed downregulated expression of specific proteins with well-established links to tumor metastasis, such as SLC25A15, DIRAS2, PLA2R1, and MTARC1." (PMID 36106120, 2022).
MTARC1 also shares sentences with these, for which no sentence is quoted: all (4 papers); non-alcoholic steatohepatitis (4); bladder cancer (2); coronary artery disease (2); liver cirrhosis (2); alcohol cirrhosis (1); cancer (1); dyslipidemia (1); gallstones (1); gout (1); hyperlipidemia (1); hypertriglyceridemia (1); lymphoma (1); microcephaly (1).